MCL1 (MCL1 apoptosis regulator, BCL2 family member)
Diseases named in the same sentence as MCL1 in open-access papers (continued):
Sharing a sentence is not in itself a finding about the gene and the disease.
cancer (continued). "The inhibition of two major anti-apoptotic proteins, Bcl-xL and Mcl-1, appears essential to destroy chemoresistant cancer cells." (PMID 24103422, 2013). "Taken together, these results suggest that the EGFR/ERK pathway has a potential role in the regulation of Mcl-1 protein levels in cancer cells of the BL subtype of TNBC." (PMID 23601074, 2013). "We have previously shown that the sensitivity of cancer cells to Apo2L/TRAIL-mediated cell death is greatly increased when the anti-apoptotic Bcl-2 family member Mcl-1 is downregulated by sorafenib." (PMID 24086526, 2013). "Recent genome-wide research suggests that Mcl-1 is subject to increased gene copy number across more than two dozen cancer types." (PMID 24025188, 2013). "Mcl-1 is an antiapoptotic protein in the Bcl-2 family member that is highly regulated in normal cells, and when dysregulated, it contributes to cancer." (PMID 24147107, 2013). "In this report, we characterize the novel α-helix mimetic JY-1-106 that disrupts the interactions between both Bcl-xL and Mcl-1 with Bak, which leads to apoptosis through the mitochondrial pathway in human cancer cells." (PMID 23680104, 2013). "The anti-apoptotic protein Mcl-1, is among the most frequently amplified genes in human cancer including NSCLCs." (PMID 23418490, 2013). "Recently investigators determined that MCL-1 was targeted by several miRNAs in various types of cancer." (PMID 23750239, 2013). "Exploiting drug regimens targeting pathways that down-regulate Mcl-1 expression is therefore a current strategy in cancer therapy." (PMID 24025188, 2013). "Mcl-1 gene expression was higher in all cancer cell lines tested than HPDEC cells at both the RNA and protein levels." (PMID 24025188, 2013). "All the cancer cell lines that express relatively high levels of Bcl-xL and Mcl-1, and the H23 line, which shows strong Mcl-1 expression and low Bcl-xL expression, demonstrate resistance to various chemotherapy agents including cisplatin, SAHA and ABT-737." (PMID 23680104, 2013). "Collectively, these data convincingly suggest that JY-1-106 is a pan-Bcl-2 inhibitor capable of antagonizing the two distinct subclasses of anti-apoptotic proteins, Bcl-2/xL and Mcl-1, both of which are critical for cancer cell survival." (PMID 23680104, 2013). "We have previously shown that sorafenib sensitizes Apo2L/TRAIL-resistant cancer cells by down-regulating the expression of Mcl-1." (PMID 24086526, 2013). "Recent studies demonstrated that cancer cells rapidly develop resistance to ABT-737 through the up-regulation of Mcl-1 and that the down-regulation of Mcl-1 restores the sensitivity to ABT-737." (PMID 23680104, 2013). "Previously study revealed that upon IL-6 treatment, Mcl-1 was rapidly up-regulated peaking at 4–8 h in human cancer cells." (PMID 23825534, 2013). "Overexpressed Bcl-xL and Mcl-1 in cancer cells, localized at the outer membrane of mitochondria, can prevent PUMA or Bim-related Bax activation and further prevent Bax-related mitochondrial fission and apoptosis." (PMID 23680104, 2013). "Cancer cell survival is dependent upon up-regulation of the pro-survival response, mediated by anti-apoptotic proteins such as Mcl-1." (PMID 24025188, 2013). "Overexpression of Mcl-1 is observed in various cancers, rendering cells resistant to apoptosis induced by chemotherapy agents." (PMID 23840208, 2013). "FE enhanced apoptosis in cancer cells that responded to treatment with three chemotherapeutic drugs with downregulation of the anti-apoptotic proteins Bcl-xL and Mcl-1." (PMID 23303302, 2013). "The expected advantage of targeting of both the Bcl-2 and Mcl-1 mechanisms of apoptosis resistance was demonstrated in various types of cancers." (PMID 23483560, 2013). "Previous studies have shown that high Mcl-1 level is an important factor for cancers to escape apoptosis." (PMID 24025188, 2013).
cancer (continued). "More recently, the sensitivity of cancer cells to antimitotic drugs has been shown to have a dependence on the ability of cyclin B1/Cdk1 to phosphorylate and increase the degradation of Mcl-1 in order to enhance apoptosis." (PMID 24058878, 2013). "Mcl-1 is an antiapoptotic member of Bcl-2 family and increased Mcl-1 protein level is commonly observed in various types of cancers, including HCC." (PMID 23594563, 2013). "Our current analyses demonstrate in principle that the expression of USP9X, Mcl-1 and Bcl-xL contributes to chemoresistance in cancer cells." (PMID 23171055, 2012). "Whereas, SG511 produced a marked decrease in the levels of Mcl-1, a short-lived protein critical for cancer cell survival." (PMID 22266706, 2012). "Mcl-1 also appears to be an important factor involved in resistance to cancer therapies, and its downregulation has proved effective at inducing apoptosis." (PMID 23284704, 2012). "In accordance with our results, Elk-1-dependent regulation of Mcl-1 expression has been described with other types of cancer." (PMID 23158473, 2012). "Earlier, Mcl-1 has been shown to contribute in resistance of cancer cells to chemotherapeutic agents, however reports on its role in radiation induced apoptosis and radioresistance are rare." (PMID 22873792, 2012). "Mcl-1 is an anti-apoptotic member of the Bcl-2 family that plays a key role in normal development, but also in pathologies such as cancer." (PMID 23024798, 2012). "Mcl-1 is the anti-apoptotic protein, which regulates intrinsic apoptosis induction at the mitochondrial level, and is often over-expressed in human cancers." (PMID 22942733, 2012). "For example, amplification of the Mcl-1 gene is a frequent somatic event in human cancer and genetic alterations that activate anti-apoptotic proteins of the Bcl2 family such as Bcl2 or Mcl-1 occur in hematopoietic malignancies." (PMID 23145067, 2012). "Mcl-1 is member of the B-cell lymphoma family of anti-apoptotic proteins and is an active target in cancer research." (PMID 23216940, 2012). "Because of the importance of Mcl-1 in cancer, we further studied the Mcl-1 stabilization that occurs upon TPA-induced ERK activation in BL41-3 cells." (PMID 23056582, 2012). "Collectively, SG511, a novel fiber chimeric oncolytic adenovirus, sensitizes cancer cells to apoptosis by reducing anti-apoptotic Mcl-1 protein levels." (PMID 22266706, 2012). "Inhibition of ERK activation/Thr 163 phosphorylation represents a promising approach for promoting Mcl-1 degradation and drug sensitivity in these cancer cells." (PMID 23056582, 2012). "Some cancer-related genes are located in these highly common, early appearing RARs: MCL1, CTSK, ARNT, S100A10, PTK2, PTP4A3, and PSCA in the RAR-Gs; and DLC1, PINX1, and GATA4 in the RAR-Ls." (PMID 22938721, 2012). "While ABT-737 has been shown to be a promising therapeutic agent, it is unlikely to be effective as a single agent in solid tumors resulted from its low affinity with Mcl-1 and high level of Mcl-1 expression in cancer cells." (PMID 23284992, 2012). "Overexpression of Mcl-1 has been found in a wide range of cancer tissues, as well as cancer cell lines." (PMID 23284704, 2012). "The aim of the present work was to investigate how Mcl-1 is regulated in cancer cells and identify cell specific RNA binding proteins (RBPs) involved in promoting the inclusion of the second exon of the Mcl-1 gene." (PMID 23284704, 2012). "They further demonstrated the ability of miR-29 to inhibit expression of Mcl-1 protein and sensitize cancer cells to TRAIL cytotoxicity through targeting a putative target site in the 3′UTR of Mcl-1 mRNA." (PMID 23075324, 2012).
cancer (continued). "It has been demonstrated in this regard that a reduction in the Mcl-1 levels in WP1130-treated cancer cells parallels the inhibition of USP9X activity." (PMID 23171055, 2012). "Our present data clearly demonstrate that the overexpression of Mcl-1 in coordination with Bcl-2/Bcl-xL expression protects cancer cells from apoptosis." (PMID 23171055, 2012). "Our observations confirm previous studies indicating that STAT3 inhibition downregulates survivin or Mcl-1 in various cancers." (PMID 22280969, 2012). "This contrasts with what is observed in normal fibroblasts, but parallels the emerging findings showing that Mcl-1 degradation via this pathway is often impaired in cancer." (PMID 23056582, 2012). "Impaired degradation leading to the maintenance of Mcl-1 expression is an important determinant of drug resistance in cancer." (PMID 23056582, 2012). "Silencing MCL-1 by RNA interference increases the sensitivity of several cancer cell lines to ABT-737 while ectopic expression of MCL-1 can render cells resistant to ABT-737." (PMID 22898329, 2012). "Considered initially as oncogenes, the prognostic impact of BCL-2/MCL-1 for various type of cancer is debated due to their dual function on cell death and cell proliferation." (PMID 21401964, 2011). "This implies that current targeted approaches need to influence the balance between Bim and Mcl-1 to efficiently affect cancer cell survival." (PMID 21899728, 2011). "ABT-737, when used alone in different cancer cells, showed up regulation of Mcl-1 protein expression." (PMID 21760983, 2011). "Although the endogenous expression of Mcl-1 varied, bortezomib induced the accumulation of Mcl-1 in various cancer cells." (PMID 22078414, 2011). "Mcl-1 appears to be crucial even for the subpopulation of BT474 that have features of cancer initiating cells, as its depletion significantly reduces the number of mammospheres these cells can form." (PMID 21899728, 2011). "Previous reports have indicated that the anti-cancer effect of gossypol was due to its ability to interfere with the functions of Mcl-1, Bcl-2 and Bcl-xL (highest to lowest affinity) proteins." (PMID 21750559, 2011). "Overexpression of BCL-2 and associated anti-apoptotic proteins Bcl-xL, Mcl-1, and BCL-W occurs in substantial subsets of common cancer types that include pancreatic, ovarian, lymphoma, multiple myeloma, lung adenocarcinoma, prostate adenocarcinoma, etc." (PMID 21760983, 2011). "Cancer cells have deregulated apoptotic pathways, where increased expression and stability of anti-apoptotic proteins Mcl-1 and Bcl-2 increases resistance to apoptosis." (PMID 21730980, 2011). "In this study, we show that two dynamin inhibitors called the MiTMABs induce cytokinesis failure and induce apoptosis in cancer cells and this appears to correlate with low expression of the anti-apoptotic proteins Bcl-2 and Mcl-1." (PMID 21708043, 2011). "Various drugs that target Bcl-2 and Mcl-1 have been tested for their abilities to induce apoptosis in cancer cells." (PMID 21949692, 2011). "This feature is exploited in cancer therapy, as inhibition of transcription and/or translation can rapidly diminish Mcl-1 levels in cells the survival of which mainly relies on Mcl-1 expression." (PMID 21750559, 2011). "A recent study illustrated that the overexpression of Mcl-1 and Bcl-xL inhibited PE immunotoxin-induced cancer cell death." (PMID 21305058, 2011). "When cancer cells resistant to ABT are pre-treated with 2DG, the protein levels of Mcl-1 remain the same, but Bak-Mcl-1 association is lost, sensitizing cells for ABT-induced apoptosis." (PMID 21949692, 2011). "Others have shown that decreased Mcl-1 expression is effective for sensitizing cancer cells to ABT-737 and induce apoptosis." (PMID 21915275, 2011). "In the Mcl-1/Bak fluorescence resonance energy transfer (FRET) assay, 17 displayed inhibitory activity towards the Mcl-1 protein, a cancer drug target involved in apoptosis." (PMID 20948911, 2010).
cancer (continued). "Bcl-2 and Mcl-1 are often highly expressed in chemotherapy-resistant cancers and prevents apoptosis by inactivating pro-apoptotic Bax and Bak." (PMID 20663232, 2010). "Further, it was demonstrated that Sorafenib-induced apoptosis resulted in down-regulation of Mcl-1, caspase activation and cytochrome c release in different cancer cells." (PMID 20950443, 2010). "Of these genes, TNFRSF1A and TRADD were found to be upregulated since they work as the trigger molecules of the apoptotic cascade in cancer cells whereas antiapoptotic genes MCL-1 and LTBR were found to be downregulated." (PMID 20673323, 2010). "Elevated levels of Mcl-1 have been reported for a number of solid and hematopoitic cancers, e.g. CLL and in AML and ALL upon relapse." (PMID 21304176, 2010). "Such rapid turnover of Mcl-1 highlights the quick response by cancer cells once they encounter proteasome stress, switching the phenotype from cell survival to programmed cell death." (PMID 21170316, 2010). "The main contribution of any combination partner, such as genotoxic drugs commonly used in cancer therapy, must therefore be the neutralisation of Mcl-1 and/or A1." (PMID 20576107, 2010). "CXCL12 producing carcinomas cultured on poly-HEMA displayed heightened Bim and loss of Mcl-1 and Bcl-2 preceding cytochrome c release, and caspase-9 activation." (PMID 20877573, 2010). "Several of the proteins that play important regulatory roles in cancer progression and apoptosis have short half-lives (e.g. cyclin D1 (∼25 min); c-Myc (∼25 min); myeloid cell leukemia-1 (Mcl-1) (∼40 min)." (PMID 19412536, 2009). "In our study, we observed gradual increases in MCL-1 and BCL-XL protein levels, both of which are implicated in cancer progression." (PMID 19698101, 2009). "So, MCL-1 is one of the important survival factors for cancer cells and is a potent target of cancer treatment." (PMID 18789152, 2008). "The antiapoptotic Bcl-2 family member, MCL-1 is normally up- and down-modulated in response to environmental signals and conditions in a normal cell, but is constitutively expressed in cancer where it promotes cell survival and drug resistance." (PMID 18789152, 2008). "Resistance to ABT-737 mediated by Mcl-1 provides an example of the complexity involved in targeting pro-survival Bcl-2 family members in cancer." (PMID 19079626, 2008). "Activation of Stat3 usually leads to the expression of downstream genes, Bcl-xL, survivin, and Mcl-1, that are important for cancer cell survival and chemoresistance." (PMID 17311011, 2007). "Additionally, MCL1, a protein frequently overexpressed in cancer, is stabilised by HTLV HBZ, which disrupts the Skp1‐Cul1 complex and thus prevents the degradation of MCL1." (PMID 40819216, 2026). "Chronic conditions, particularly cancer, were major drivers of MCL-1 dysregulation." (PMID 42105027, 2026). "The splicing factor SRSF1 and antiapoptotic protein Mcl-1, including its isoforms Mcl-1L and Mcl-1S, play significant roles in cancer development; however, the regulatory mechanisms of the SRSF1-Mcl-1 axis in GC remain unclear." (PMID 42293332, 2026). "The MCL-1 gene is crucial in enabling cancer cells to resist apoptosis." (PMID 39859117, 2025). "Current research suggests that small molecule antagonists targeting BCL-XL and MCL-1 could improve outcomes for cancers resistant to BCL-2 inhibition." (PMID 40204952, 2025). "Additionally, therapeutic approaches that target MCL-1 are being explored across various cancers, including HCC." (PMID 40380182, 2025). "While previous studies have successfully applied multi-tiered in silico methods to optimize anti-cancer scaffolds, our study is distinct in its focused application to Mcl-1 inhibition in the context of AML, leveraging a series of 1,2,4-triazolo[4,3-b]pyridazine derivatives." (PMID 40979648, 2025). "Elevated MCL1 levels suppress cell death, making cancer cells more resistant to treatments." (PMID 39985075, 2025).
cancer (continued). "Since this compound targets both BCL-2 and MCL-1—important for short-term and long-term anti-apoptotic defenses, respectively—its dual action supports that it is effective against aggressive and resistant cancer subtypes." (PMID 39859117, 2025). "The suppressive effect of MCL1 inhibition on mTORC1 in cancer cells described here could be a desirable—although unintended or unexpected- effect, given the tumor-promoting function of mTORC174–76." (PMID 41326406, 2025). "Thus, BH3 mimetics, such as Navitoclax, Venetoclax, and MCL-1 inhibitors have been exploited for cancer therapy and have proven clinical activity in some leukemias and lymphomas." (PMID 39996719, 2025). "In addition, the DepMap database confirms that BCL2L1 is one of the major genes that modulates MCL1 dependency in cancer cell lines." (PMID 41438049, 2025). "Overall, our multidimensional, integrated genomic approach identified MCL1 as a promising therapeutic target in several BCL2L1-methylated pediatric cancers, offering a translational strategy to identify patients most likely to benefit from MCL1 inhibitor therapy." (PMID 39846250, 2025). "Prior studies suggested that deleting MCL1 sensitizes cancer cell lines to chemotherapy." (PMID 40909578, 2025). "For instance, BOK is frequently deleted in cancers while MCL-1 is often amplified." (PMID 39996719, 2025). "MCL1 has been described before as the driver of 1q gain in other cancers, but was not linked to treatment with MCL1 inhibitors." (PMID 40694850, 2025). "Cancer cells may also enhance the expression of anti-apoptotic proteins, including MCL-1 and BCL-2, which are known to confer resistance to CDK inhibitors by suppressing apoptotic signaling." (PMID 40076816, 2025). "Therapeutic strategies such as the use of pemetrexed, an antifolate chemotherapy drug, have shown promise in preclinical and clinical settings by disrupting the Noxa-Usp9x-Mcl-1 pathway, highlighting the significant potential of Mcl-1-targeted interventions to improve cancer treatment outcomes." (PMID 40841912, 2025). "As metabolism of cancer cells in vitro may differ from that of tumors in vivo, we aimed to assess the role of MCL1 in regulating tumor metabolism in vivo." (PMID 41326406, 2025). "Similarly, a BCL2 family inhibitor MCL1 is overexpressed in cancers, promoting resistance to anticancer drugs." (PMID 39985075, 2025). "Moreover, while most existing in silico Mcl-1 inhibitor studies emphasize general anti-cancer utility, our work uniquely bridges prior experimental cytotoxicity data with structure-based modeling focused on AML." (PMID 40979648, 2025). "Targeting the miR-375/MCL1 axis could provide a promising approach to enhance the effectiveness of chemotherapy in treating this type of cancer." (PMID 39931465, 2025). "Myeloid cell leukemia 1 (Mcl-1) is a key survival factor in a wide range of human cancers." (PMID 40733283, 2025). "MCL1 apoptosis regulator (Mcl-1) plays a crucial role in impeding the apoptosis of cancer cells." (PMID 39935428, 2025). "Cancer drug therapy: Chemotherapy and targeted therapy drugs may impact the expression of MCL1 by modulating the cell apoptosis pathway." (PMID 40026415, 2025). "The gene, myeloid cell leukemia-I (MCL-1) gene also significant role in primary stages of cancer." (PMID 40834023, 2025).